CRP (C-reactive protein)
Diseases named in the same sentence as CRP in open-access papers (continued):
Sharing a sentence is not in itself a finding about the gene and the disease.
anemia (continued). "Laboratory data showed a normochromic normocytic anemia with a hemoglobin of 9.3 g/dL, white cell count of 14.61x10e3/μL (83.1% neutrophils), serum creatinine 1.46 mg/dL and C-reactive protein of 32.11 mg/dL." (PMID 35959179, 2022). "Among biological findings, anemia, elevated CRP, and IL-6 were also significant predictors for prematurity in association with SARS-CoV-2 infection during pregnancy." (PMID 36579593, 2022). "They found that clinical symptoms, such as low-grade fever, abdominal/lumber pain, and anemia, IL-6 and C-reactive protein (CRP) were significantly higher in IgG4-AAs and IgG4-PA than in IgG4-RF." (PMID 35440292, 2022). "SAH patients with poor initial clinical and radiographic condition and certain laboratory findings (lower Hb and higher c-reactive protein, glucose and troponin at admission) were more prone to anemia and/or the need for RBCT during SAH." (PMID 36456587, 2022). "C-reactive protein (CRP) levels elevated prior to treatment or during the course of treatment, as well as cancer cachexia, hypoalbuminemia, anemia and weight loss, significantly impact the prognosis of cancer patients." (PMID 35331196, 2022). "Biological markers showed an inflammatory syndrome with elevated serum CRP levels (range, 13–112 mg/L) and polyclonal hypergammaglobulinemia (range, 17.7–33 g/L) in all patients, anaemia in four and elevated serum VEGF levels in the four patients tested." (PMID 35846183, 2022). "Severe anaemia (n=10, 71%), elevated ferritin (n=6, 43%), positive C-Reactive Protein (n=4, 28%) and deranged D-dimer (n=11, 78%) were noted." (PMID 35664398, 2022). "Histopathologic lymph node features, anemia, elevated CRP and IL6 levels, splenomegaly, and hypoalbuminemia indicated multicentric Castleman (MCD) disease." (PMID 35399163, 2022). "When predictors of survival were analyzed in the group of patients with available serum iron parameters, age, hemoglobin, CRP, anemia etiology, ferritin and transferrin were predictors of survival." (PMID 35895618, 2022). "The possible reason is that the control group continued to have low levels of anemia indicators after surgery, resulting in a weaker ability to fight inflammatory responses, manifested as high CRP on the 7th day after surgery." (PMID 36684362, 2022). "We supplemented our findings with a statistical analysis of the diagnostic value of hepcidin, IL-6, TNF-a, CRP, and SAA1 in the examination and differentiation of anaemia in lung cancer patients." (PMID 36612220, 2022). "In HIV-infected individuals, low body mass index, moderate-severe anaemia, low CD4 counts and high CRP were associated with lower physical activity and capacity." (PMID 35061774, 2022). "Treatment with rhGH prior to KT was associated with superior growth outcome in prepubertal kidney transplant recipients, which was related to better transplant function, lower CRP, less anemia, lower steroid exposure, and earlier maturation after KT." (PMID 34542703, 2022). "Anemia-related diagnostics such as elevated ferritin, CRP, and erythrocyte sedimentation rate (ESR) were identified, which partially reverted at 60 days of ATT." (PMID 36106202, 2022). "Older age (> 55 years), elevated waist circumference, NT-pro BNP > 125 pg/mL, anemia, C-reactive protein ≥ 3 mg/dL, and troponin T ≥ 14 pg/mL were independent predictors of walking shorter distances." (PMID 36333405, 2022). "Especially since we can predict which operative lung cancer patients will develop anaemia during hospitalization using hepcidin, IL-6, and CRP testing and include these patients in anaemia prevention treatment." (PMID 36612220, 2022). "The most common clinical laboratory findings at the acute MIS-C stage included elevated C-reactive protein (100%) and d-dimer (93.7%), anaemia (87.5%), thrombocytosis (56.2%), hyperferritinemia (50%), elevated fibrinogen (50%), and neutrophilia (50%)." (PMID 36510129, 2022).
anemia (continued). "While CRP, anemia, and ferritin levels quickly improved in all groups regardless of initial degree of abnormality, ESR was slower to normalize." (PMID 36680134, 2022). "Anemia has a high prevalence among patients undergoing colorectal surgery and rational treatment requires early assessment of serum iron parameters and C-reactive protein." (PMID 35895618, 2022). "Multiple regression analysis adjusted for age, sex, Encephalitozoon carriage, serum CRP, and anemia was used to test if HAZ score predicted relative percentages of monocyte subtypes." (PMID 35720335, 2022). "Third, a subset of elderly patients with anemia is characterized by inflammation and increased CRP levels, but it should also be emphasized that anemia seems to have an impact on survival that is independent of the CRP level." (PMID 35160156, 2022). "We report the case of an 88-year-old man with COVID-19 disease who presented at the admission with anemia, fever, oxygen desaturation (92%), and inflammatory syndrome (C-reactive protein (CRP) at 182.5 mg/L; reference range <5.0 mg/L)." (PMID 35200527, 2022). "Laboratory test results are also very similar, with all cases showing modest anemia, thrombocytosis, elevated acute-phase reactants (including both the erythrocyte sedimentation rate and CRP)." (PMID 35844576, 2022). "In addition, higher ferritin level increases C-reactive protein level in patients on hemodialysis, which could be partially explained by the disturbance of iron released from ferritin in patients with inflammation-associated anemia." (PMID 35887674, 2022). "If the patient has recovered from anemia and the serum C-reactive protein (CRP) level is significantly reduced, then the results indicate that the tubercle bacilli have been eradicated." (PMID 36578841, 2022). "Among those findings we can mention the higher D Dimer the lower transferrin that are common in anemia of chronic diseases, and the higher and abnormally elevated CRP and ferritin levels all observed in the asplenia/hyposplenism group." (PMID 36105295, 2022). "Blood tests were significant for anemia (hemoglobin 6.5 gram/dL), hypoalbuminemia (albumin 1.5 gr/dL) and elevated inflammatory markers (CRP 94 mg/L, normal <5 mg/L)." (PMID 36466854, 2022). "On multivariate analysis, anemia etiology, younger age and low CRP remained significant independent predictors of improved survival." (PMID 35895618, 2022). "MCD is often accompanied by a systemic inflammatory response, which is characterized by a variety of laboratory and imaging abnormalities, such as anemia, hypoalbuminemia, elevated CRP and ESR levels, abnormal liver and kidney function, and serous effusion." (PMID 35655778, 2022). "Elevated ESR and CRP levels, combined with anemia, are highly indicative of the necessity for further work-up." (PMID 35795624, 2022). "Two patients had throughout the study elevated levels of fecal calprotectin (mean levels of 658 and 930 μg/g), anemia (hemoglobin levels of 83 and 130 g/l), and elevated CRP levels (31 mg/L in both)." (PMID 35679312, 2022). "The laboratory test results of UCD patients are usually normal, but anemia, increased C-reactive protein (CRP) levels, increased erythrocyte sedimentation rate (ESR), and other abnormalities can be present." (PMID 35655778, 2022). "Laboratory investigations showed obviously increased CRP and SF with slightly macrocytic anemia (Hb 100 g/L and MCV 111.2 g/L) and leukopenia (WBC 3.04*109/L)." (PMID 35547205, 2022). "Among the patients with both high hs-CRP level and malnutrition, the prevalence of anemia, chronic kidney disease (CKD) and the level of pro-BNP increased in a stepwise manner, while the level of eGFR and left ventricular ejection fraction (LVEF) decreased." (PMID 35719150, 2022). "Initial workup includes complete blood count, metabolic panel, peripheral smear, anemia panel, erythrocyte sedimentation rate, C-reactive protein, and lactate dehydrogenase." (PMID 36561590, 2022).
anemia (continued). "The serum sample of those diagnosed with anaemia will be refrigerated and sent to a local laboratory to analyze ferritin and CRP." (PMID 38463717, 2022). "Abnormal results such as anemia (32/632, 5.1%), hypoalbuminemia (116/662, 17.5%), hypoproteinemia (125/655, 19.1%), hypocobalaminemia (98/647, 15.1%), and increased CRP concentrations (145/267, 54.3%) were identified." (PMID 35739843, 2022). "al. found greater morbidity, functional dependence, hypoalbuminemia, anemia, admission to the ICU, and elevated acute phase reactants (CRP) as independently associated with prolonged hospital stay in an acute-geriatric unit." (PMID 36140006, 2022). "In laboratory examinations, patients predominately showed anemia, hypoalbuminemia, elevated CRP levels, and mildly elevated Cr levels." (PMID 35215942, 2022). "Lymphopenia, elevated C-reactive protein (CRP), anemia, and hypoproteinemia were all shown to be major factors in the disease's progression." (PMID 35127069, 2022). "A 64-year-old man had progressive anemia, proteinuria, polyclonal hypergammaglobulinemia, and elevated C-reactive protein (CRP) since 2008." (PMID 35212301, 2022). "For those with anaemia identified by the hemocue, 4 mL of blood will be extracted to separate the serum for the ferritin and CRP measurements." (PMID 38463717, 2022). "In the first case, a patient in their 60s was referred to the SCAN pathway because of abdominal pain, anemia, and a raised C-reactive protein level." (PMID 34983789, 2022). "Laboratory findings revealed hyperglycemia, elevated erythrocyte sedimentation rate (ESR) of 118 mm/hour, and elevated C-reactive protein (CRP) of 6.58 mg/dL, and slight anemia with hemoglobin of 12.1 g/dL." (PMID 35331322, 2022). "The PSQI scores were significantly higher in the elderly, patients with long duration of dialysis, patients with elevated CRP, patients with substandard anemia, and patients with substandard calcium and phosphorus (P > 0.05)." (PMID 34867112, 2021). "Laboratory tests showed thrombocytopenia, elevated C-reactive protein, hypoalbuminemia, anemia and renal dysfunction." (PMID 33402219, 2021). "The blood tests revealed severe renal dysfunction, anemia, and elevated levels of C-reactive protein and myeloperoxidase ANCA." (PMID 34126959, 2021). "The most significant abnormalities are anemia, increased C-reactive protein, and low serum albumin levels." (PMID 33923423, 2021). "Laboratory tests showed severe anemia (hemoglobin 65 g/L), leukopenia, trombocytopenia, and elevated levels of C-reactive protein (98 g/L)." (PMID 34835343, 2021). "Blood tests showed marked lymphopenia, moderate anemia with inadequate reticulocytosis, altered hemolytic markers and increased C reactive protein (CRP) and lactates (2.5 mmol/L)." (PMID 33672504, 2021). "Its impact was independent of gender and other known risk factors such as congestion as an early sign of beginning cardiac deterioration (represented by mean PAP), inflammation (represented by CRP), and anemia (represented by hemoglobin levels)." (PMID 34733892, 2021). "Further, the calculated intake of iron and vitamin A was much higher and the prevalence of anaemia, ID, and elevated CRP/AGP was much lower in Chamwino than in Kilosa." (PMID 34066852, 2021). "Similar to published data, anemia, lymphopenia, and elevated CRP were common findings in cancer patients." (PMID 33159569, 2021). "Abdominal pain, hematochezia, elevation of CRP level or erythrocyte sedimentation rate, and anemia were the most common findings in rectal IMTs." (PMID 34414993, 2021). "The odds ratios (ORs) and 95% confidence intervals for elevation (top quartile) of IL-1α, IL-1β, IL-6, IL-8, and CRP in umbilical cord blood are shown for maternal nutrition (anthropometrics and anemia) and infections in pregnancy." (PMID 34836049, 2021). "Lab abnormalities, such as anemia, thrombocytopenia, hypoalbuminemia, and elevated C-reactive protein (CRP) are common." (PMID 33512649, 2021).
anemia (continued). "Among laboratory tests, elevation of acute phase reactants, ESR and CRP, neutrophilic leukocytosis, high platelet count and anemia were significantly more frequent in patients with GS and AOM." (PMID 33830308, 2021). "The laboratory tests revealed anemia, an increased number of monocytes, and a mildly increased C-reactive protein." (PMID 34943324, 2021). "His laboratory findings showed anemia, thrombocytopenia, and coagulopathy with a high level of C-reactive protein (CRP)." (PMID 33787566, 2021). "We noted a significant increase in serum CRP and in the prevalence of anemia with an increase in WC." (PMID 33914792, 2021). "This retrospective study performed an exploratory evaluation of patients admitted to an emergency department considering the concentration of Hb and CRP as markers of anemia and inflammation, respectively." (PMID 34830693, 2021). "The common laboratory findings were elevated CRP level or erythrocyte sedimentation rate (5 of 9 cases) and anemia (4 of 9 cases)." (PMID 34414993, 2021). "After treatment with tocilizumab, the patient’s C-reactive protein (CRP) elevation, anemia, and polyclonal gammopathy improved." (PMID 34107915, 2021). "Certain AE present in more than 50% patients include pyrexia, increased CRP and Ferritin, hypotension, tachycardia, neutropenia, thrombocytiopenia, anemia, and elevated D-dimer(> 0.55)." (PMID 34518515, 2021). "Laboratory predictors of a LAM+ve status included renal dysfunction, P = 0.044, severe anaemia, P = 0.0116, and an elevated C-reactive protein, P = 0.0131." (PMID 34394971, 2021). "Of the indeterminate results, 32 (82%) had an elevated CRP (>10); 38 (97%) had a low serum albumin (<35); anaemia was present in 26 patients (67%); and thrombocythemia was found in 27 (69%) patients." (PMID 33919426, 2021). "After intravenous tocilizumab (700 mg every 2 weeks) was started, his C-reactive protein elevation, anemia, and polyclonal gammopathy improved." (PMID 34107915, 2021). "The laboratory workup showed microcytic hypochromic anemia (Hg 11.2 g/dL), normal leukocyte count with relative lymphocytosis, altered liver panel, thrombocytopenia, and elevated C reactive protein (CRP)." (PMID 33728162, 2021). "Absolute neutrophil, monocyte and platelet counts, CRP, and anemia are easily accessible blood-based biomarkers to assess the systemic inflammation." (PMID 34055606, 2021). "Regarding laboratory work, males displayed anemia, hypoalbuminemia, and elevated CRP more frequently than women." (PMID 34436194, 2021). "Elevated acute phase reactants (ESR, CRP) were common in this study; although leukopenia, anemia, and thrombocytopenia were seen in a considerable number of the patients, these abnormalities were also reported in other studies." (PMID 34007286, 2021). "The blood test revealed mild anemia (Hb 9.8 g/dL), normal white blood cell count (7400/μL), and increased C-reactive protein (CRP) level (11.08 mg/dL)." (PMID 33786105, 2021). "In Chamwino, multiple MN deficiencies (ID, VAD, and ZnD) and reported malaria were associated with anaemia, ID, and VAD; elevated CRP/AGP (inflammation) predicted VAD in Chamwino and anaemia, ID, and VAD in Kilosa." (PMID 34066852, 2021). "Elevated C-reactive protein (CRP) levels is an independent factor known to increase the prevalence of anemia in patients with IBD." (PMID 34836263, 2021). "Serum investigations were remarkable for normocytic, normochromic anemia (hemoglobin, 10.6 g/dL), leukocytosis (leukocyte count, 17.1 × 109/L), and an elevated C-reactive protein (CRP, 53 mg/L)." (PMID 34663231, 2021). "At presentation, CD patients showed significantly more anemia, higher C-reactive protein (CRP) levels, and low proportion of albumin <3.5 g/dL compared with UC patients." (PMID 37206943, 2021). "In our cohort, it significantly correlated both ALBI score and NLR with cachexia related blood tests such as anaemia (p < 0.001) and CRP level (p < 0.001)." (PMID 34707147, 2021).
anemia (continued). "The PSQI score was significantly higher in the elderly, patients with long duration of dialysis, patients with elevated CRP, patients with substandard anemia, and patients with substandard calcium and phosphorus, with statistical significance (P < 0.05)." (PMID 34867112, 2021). "After 14 days of therapy with vancomycin and cefepime, the inflammatory markers were significantly lower but still elevated (CRP of 36 mg/L), anaemia was stable (9,3 g/dL) and thrombocyte count was normal (221.000/mcL)." (PMID 34130635, 2021). "This correlation was still significant for 67% of patients with both anemia and inflammation, suggesting that the increase in CRP explains nearly 45% of the decrease in Hb." (PMID 34830693, 2021). "17.3% of the study population had higher CRP 24.7% and 31.9% of subjects had ID and anemia, respectively." (PMID 33914792, 2021). "Laboratory findings are similar to those found in acute anaplasmosis and ehrlichiosis: elevated CRP, elevated hepatic enzymes, anaemia, thrombocytopenia, leukopenia or leucocytosis." (PMID 34130635, 2021). "We analysed the variations of clinical manifestations of the severity of SCD (VOC occurrence, number of hospitalizations, sanguine transfusion, severity of anemia, CRP, and body mass index (BMI)) according to the Hp genotype in SS patients." (PMID 34721583, 2021). "Biomarkers such as C-reactive protein (CRP) and alpha-1 acid glycoprotein (AGP) are used to adjust iron deficiency measures and improve estimates of anemia prevalence and causes." (PMID 33407284, 2021). "The analysis of laboratory results showed that patients with anemia had higher values of C-reactive protein, leukocytes, neutrophils and platelets." (PMID 33529195, 2021). "Four years later, in 2016, the patient presented with an elevated erythrocyte sedimentation rate (ESR) (72 mm) and C-reactive protein (CRP) (56.1 mg/L), thrombocytosis (501 × 10^9/L) and anaemia (haemoglobin 7.4 mmol/L)." (PMID 33715142, 2021). "Anaemia was seen in 15 (39.5%) and 27 of 38 (71.1%) patients had an elevated C-reactive protein (CRP)." (PMID 34209322, 2021). "Systemic biological signs were more pronounced in CWD patients, with higher CRP levels, lower albuminemia levels, and more anaemia and thrombocytosis." (PMID 34112875, 2021). "Blood tests show anemia, eosinophilia, and increased C-reactive protein (CRP), lactate dehydrogenase (LDH), and creatine kinase (CK,) which are indicators of ischemia of various organs." (PMID 33265990, 2020). "This patient had anemia, thrombocytopenia, and eosinopenia and showed elevated liver enzymes and increased CRP and LDH concentrations." (PMID 31769398, 2020). "Increased levels of CRP and liver enzymes were detected in more than 80% of patients, followed by anemia, thrombocytopenia, and elevated serum concentration of LDH." (PMID 31769398, 2020). "Anemia prevalence ranged between 14.2% and 20.8% during the observation period and anemia was associated with lower FEV1, DLCOc, and CRP elevation." (PMID 32922186, 2020). "Non-survivors in our study had higher levels of inflammatory markers (WBC, procalcitonin, CRP, and IL-6) as well as lower anemia related parameters (RBC, hemoglobin, and hematocrit), which concurs with current publications." (PMID 33198124, 2020). "Laboratory results showed anemia (8.2 g/dl), increased C-reactive protein (CRP) levels and normal LDH levels." (PMID 32375712, 2020). "LAVE was effective in optimizing RIs for AST, ALT, GGT iron-markers and CRP by reducing influence of latent anemia and metabolic diseases." (PMID 32645006, 2020). "In the nomogram, ALT was the largest predictor for KD (100 points), followed by WBC (96 points), PCT (57 points), CRP (53 points), and albumin (58 points), while anemia was the smallest predictor (40 points)." (PMID 32792679, 2020). "Those with both high ferritin and high CRP, consistent with the presence of anaemia of inflammation, had a negligible haemoglobin response to iron infusion." (PMID 32537137, 2020).